SF3B3 (splicing factor 3b subunit 3)
Description:
Component of the 17S U2 SnRNP complex of the spliceosome, a large ribonucleoprotein complex that removes introns from transcribed pre-mRNAs. The 17S U2 SnRNP complex (1) directly participates in early spliceosome assembly and (2) mediates recognition of the intron branch site during pre-mRNA splicing by promoting the selection of the pre-mRNA branch-site adenosine, the nucleophile for the first step of splicing. Within the 17S U2 SnRNP complex, SF3B3 is part of the SF3B subcomplex, which is required for 'A' complex assembly formed by the stable binding of U2 snRNP to the branchpoint sequence in pre-mRNA. Sequence independent binding of SF3A and SF3B subcomplexes upstream of the branch site is essential, it may anchor U2 snRNP to the pre-mRNA. May also be involved in the assembly of the 'E' complex. Also acts as a component of the minor spliceosome, which is involved in the splicing of U12-type introns in pre-mRNAs.
Synonyms: SF3b130; KIAA0017; SAP130; RSE1; STAF130
Tractability: Small molecule: a structure with a bound ligand is known; a high-quality ligand is known; it belongs to a druggable protein family. PROTAC: ubiquitination databases record sites on it; its protein half-life has been measured; a small molecule that binds it is known.
Target class: Other nuclear protein
Gene: Protein-coding gene on chromosome 16 (70,523,782 to 70,577,670, forward strand). Ensembl gene ENSG00000189091.
Subcellular location: Nucleus
Subcellular location (Human Protein Atlas): Nucleoli; Nucleoli rim; Nucleoplasm
Pathways (Reactome):
Metabolism of RNA: mRNA Polyadenylation; mRNA Splicing - Major Pathway; mRNA Splicing - Minor Pathway
Chromatin organization: CHD1 and CHD2 subfamily
Disease: Dengue Virus-Host Interactions
Gene Ontology:
Molecular function: protein binding; protein-containing complex binding; U2 snRNA binding; nucleic acid binding
Biological process: mRNA splicing, via spliceosome; negative regulation of protein catabolic process; positive regulation of DNA-templated transcription; regulation of DNA repair; regulation of RNA splicing; RNA splicing; RNA splicing, via transesterification reactions; spliceosomal snRNP assembly; spliceosome conformational change to release U4 (or U4atac) and U1 (or U11); U2-type prespliceosome assembly
Cellular component: catalytic step 2 spliceosome; nucleolus; nucleoplasm; nucleus; precatalytic spliceosome; spliceosomal complex; U11/U12 snRNP; U12-type catalytic step 2 spliceosome; U12-type precatalytic spliceosome; U12-type spliceosomal complex; U2-type catalytic step 1 spliceosome; U2-type precatalytic spliceosome; U2-type spliceosomal complex; SAGA complex; U2 snRNP
Genetic constraint (gnomAD): Loss-of-function variants: 25 observed, 122.37 expected, observed/expected ratio (o/e) 0.2, 90% interval 0.15 to 0.28. The upper end of that interval is the gene's LOEUF score, 0.28, which puts it in group 1 of 6, group 1 being the genes least tolerant of losing a copy. Missense variants: 746 observed, 1,449.7 expected, observed/expected ratio (o/e) 0.51, 90% interval 0.48 to 0.55. Synonymous variants: 547 observed, 548.31 expected, observed/expected ratio (o/e) 1, 90% interval 0.93 to 1.07.
Homologues: Orthologues: chimpanzee SF3B3 (100% identical), macaque SF3B3 (100% identical), dog SF3B3 (99% identical), mouse Sf3b3 (99% identical), rat Sf3b3 (99% identical), guinea pig SF3B3 (99% identical), pig SF3B3 (98% identical), rabbit SF3B3 (97% identical), tropical clawed frog sf3b3 (97% identical), zebrafish sf3b3 (93% identical), Drosophila melanogaster Sf3b3 (76% identical), Caenorhabditis elegans teg-4 (61% identical). Paralogues in human: CPSF1 (20% identical), DDB1 (19% identical).
Diseases named in the same sentence as SF3B3 in open-access papers:
SF3B3 is named in the same sentence as 26 diseases in open-access papers, as found by Europe PMC text mining. Sharing a sentence is not in itself a finding about the gene and the disease. The quoted sentences say what the papers report.
breast carcinoma (8 papers, 2017 to 2025). "As for SF3B3, its overexpression is associated with breast carcinoma’s late stage of progression and the poor survival of the patients." (PMID 39201614, 2024). "SF3B3 (SF3B130) a component of the SF3B complex has been found to be significantly overexpressed in ER+ breast cancers and is associated with aggressive disease and resistance to tamoxifen therapy." (PMID 29848666, 2018). "SF3B3 is a protein for spliceosome assembly, which expression has been reported to associate with cancer cell growth and prognosis of breast cancer patients." (PMID 28038442, 2017). "Regarding expressions of SF3b complex components, it was reported that SF3B1 and SF3B3 are upregulated in fulvestrant/tamoxifen-resistant breast cancer cells, and SF3B3 overexpression associates with poor relapse-free and overall survival in ER-positive breast cancer patients." (PMID 32106418, 2020). "This study demonstrates that SF3B3-regualted mTOR splicing contributes to autophagy in SF3B3-knockdown breast cancer cells." (PMID 38671459, 2024). "We then silenced SF3B3 in breast cancer cells (MCF7), cervical cancer cells (Hela) and liver cancer cells (Huh7)." (PMID 38671459, 2024). "Although less frequently than SF3B1, the mutations of SF3B3 and SF3B4, other components of the SF3b complex, are also observed in breast cancers (0.2% each)." (PMID 32106418, 2020). "SF3B3 has also been found to be amplified and highly expressed at the transcript level in basal-like breast cancers." (PMID 29848666, 2018). "Using a pooled-genome wide shRNA library screen and global proteomic profiling, we demonstrated that jerantinine A (JA) targets the cancer spliceosome through the upregulation of SF3B1 and SF3B3 proteins in breast cancer cells." (PMID 28198434, 2017). "Using a combined pooled-genome wide shRNA library screen and global proteomic profiling, we showed that JA targets the spliceosome by up-regulating SF3B1 and SF3B3 protein in breast cancer cells." (PMID 28198434, 2017). "Interestingly, knockdown of SF3B3 inhibits the cell growth of both renal cancer cells and breast cancer cells." (PMID 38671459, 2024). "A previous study reported that SF3B3 knockdown induces autophagy in breast cancer cells, but the underlying mechanism is not fully elucidated." (PMID 38671459, 2024). "There is increasing evidence that spliceosomal component genes themselves are dysregulated in breast cancer, through mutations in SF3B1 that are also observed in metastatic disease and upregulation of SF3B3 and SRSF1 in particular, which are associated with resistance to endocrine therapy." (PMID 29848666, 2018). "In breast cancer cells, autophagy induced by SF3B3 knockdown inhibits the proliferation and migration of breast cancer cells without inducing apoptosis." (PMID 38671459, 2024). "Although the up/down-regulation reports in breast cancer on SF3B3 and PGM3 corroborate our findings, there is no report concerning the ascending trend of these genes across stages." (PMID 35031021, 2022).
renal carcinoma (7 papers, 2017 to 2025). A carcinoma arising from the epithelium of the renal parenchyma or the renal pelvis. "SF3B3 expression is upregulated in renal cancer, and is associated with tumor stage and poor prognosis." (PMID 38671459, 2024). "Studies have shown that SF3B1, SF3B2, and SF3B3 can regulate target gene expression by alternative splicing to promote cancer progression, also SF3B3 controls AS in renal cancer and SF3B4 in ovarian cancer by regulating AS of RAD52." (PMID 37091785, 2023). "SF3B3 is a pro-oncogene in renal cancer and knockdown of SF3B3 in renal cancer cells significantly inhibits tumor growth in tumor-bearing mice." (PMID 33613846, 2021). "In renal cancer cells, the splicing factor SF3B3 stimulates the inclusion of exon 14 in Ezh2 transcripts." (PMID 30522506, 2018). "Previous studies have shown that SF3B3 regulates EZH2 splicing in renal cancer and HCC." (PMID 39850359, 2025). "Splicing Factor 3b Subunit 3 (SF3B3) controlled the alternative splicing of Enhancer of Zeste 2 Polycomb Repressive Complex 2 Subunit (EZH2) pre-mRNA and contributed to the tumorigenic potential of renal cancer." (PMID 31857793, 2019).
clear cell renal carcinoma (2 papers, 2018 to 2021). A malignant epithelial neoplasm of the kidney characterized by the presence of lipid-containing clear cells within a vascular network. "In clear cell renal cell carcinoma, SF3B3 overexpression was found to increase the expression of the pro-proliferative full-length isoform of EZH2 and not the commonly expressed EZH2∆14 that is found in normal tissue, thus promoting tumourigenicity in vivo." (PMID 29848666, 2018). "Further functional studies in the context of clear cell renal carcinoma show that knockdown of SF3B3 in SF3B3-overexpressing cells in vivo reduced tumour growth, highlighting the potential utility of SF3b inhibitors as a therapeutic agent for patients with SF3B3 amplification and/or overexpression." (PMID 29848666, 2018). "For example, the SF SF3B3 is upregulated and contributes to tumorigenesis by regulating EZH2 pre-mRNA splicing, representing a key prognostic factor and therapeutic target in clear cell renal cell carcinoma." (PMID 33842332, 2021).
hepatocellular carcinoma (2 papers, 2022). A malignant tumor that arises from hepatocytes. "Eventually, the LINC01348/SF3B3/EZH2/JNK/c-Jun/Snail pathway inhibits hepatocellular carcinoma progression." (PMID 34750493, 2022).
liver cancer (2 papers, 2017 to 2024). An epithelial or non-epithelial malignant neoplasm that arises from the liver. "By performing experimental evaluation using siRNA-mediated knockdown and overexpression constructs, we demonstrated that the mutants of GOLGB1 and SF3B3 can promote cell proliferation, colony formation, migration, and invasion of liver cancer cells." (PMID 28038442, 2017). "Both the knockdown cells for GOLGB1 or SF3B3 suppressed cell proliferation activity in diverse liver cancer cell lines of HepG2, Huh7, Hep3B, SNU423, and PLC." (PMID 28038442, 2017). "In addition, we could observe positive correlations of the expression levels of GOLGB1 or SF3B3 with the expression levels of CXCL8 and SOX4 in the liver cancer data of TCGA, implying the potential connection between them." (PMID 28038442, 2017).
non-small cell lung carcinoma (2 papers, 2019 to 2021). A group of at least three distinct histological types of lung cancer, including non-small cell squamous cell carcinoma, adenocarcinoma, and large cell carcinoma. "Our collective findings support a role of circRNA 100146 in the development of NSCLC and further demonstrate endogenous competition among circRNA 100146, SF3B3 and miRNAs, providing novel insights into the mechanisms underlying non-small cell lung cancer." (PMID 30665425, 2019). "For example, in non-small cell lung cancer, the circRNA 100,146 can bind and sponge miR-361-3p and miR-615-5p, which both directly inhibit the expression of the SF SF3B3, thus increasing SF3B3-mediated AS to promote the proliferation and invasion of cancer cells." (PMID 33407694, 2021).
renal cell carcinoma (2 papers, 2020 to 2021). "SF3B3 regulates EZH2 alternative splicing, and its expression is associated with poor outcome in renal cell carcinoma." (PMID 34683129, 2021). "In renal cell carcinoma, SF3B3 modulates EZH2 alternative splicing to promote carcinogenesis, and SF3B3 could be a potential prognostic factor and therapeutic target in renal cell carcinoma." (PMID 32808488, 2020).
bladder cancer (1 paper, 2017). "Indeed, GOLGB1 mutation was frequently observed in lung cancers (9%), while the SF3B3 mutation was frequently observed in bladder cancer (5.4%)." (PMID 28038442, 2017).
esophageal cancer (1 paper, 2023). A primary or metastatic malignant neoplasm involving the esophagus. "Anti‐SF3B3 autoantibody presented higher level in sera from patients with esophageal cancer than that in the normal controls." (PMID 36587394, 2023).
leukoplakia (1 paper, 2024). A white patch or plaque on a mucous membrane that cannot be characterized clinically or pathologically as any other disease. "Regarding SF3B3, it has been indicated as one of the main promoters of leukoplakia transformation into OSCC." (PMID 39201614, 2024).
liver fibrosis (1 paper, 2025). "Notably, MCM7 has been reported to positively regulate the mRNA splicing of EGFR and PDGFR through its interaction with SF3B3 in prostate cancer, suggesting its significant role in the pathogenesis of liver fibrosis." (PMID 40789837, 2025).
melanoma (1 paper, 2021). A malignant, usually aggressive tumor composed of atypical, neoplastic melanocytes. "Mutations in some of these genes of the splicing machinery, such as Serine and Arginine Rich Splicing Factor A3 and B3 (SF3A3, SF3B3), were significantly enriched in melanomas as compared to benign nevi." (PMID 34281234, 2021).
myeloma (1 paper, 2021). "Since EZH2 is overexpressed in myeloma cells in association with a poor outcome, it would be interesting to explore the potential role of alternative EZH2 splicing regulated by SF3B3 in plasma cell tumorigenesis and disease progression." (PMID 34683129, 2021). "The CERES score of four genes (ISG20, NDC1, SF3B3, UMPS) was significantly lower in the myeloma cell lines (n = 20) compared to in the other cancer cell lines (n = 769)." (PMID 34683129, 2021).
prostate carcinoma (1 paper, 2025). A carcinoma that arises from epithelial cells of the prostate gland. "Notably, MCM7 has been found to bind to the SF3B3 subunit of the RNA splicing complex, thereby regulating the expression of fibrosis-related factor receptors EGFR and PDGFR at the splicing level in prostate cancer." (PMID 40789837, 2025).
cancer (13 papers, 2017 to 2024). A tumor composed of atypical neoplastic, often pleomorphic cells that invade other tissues. "Together, our results suggest that targeting other splicing factors such as SF3B3 to compromise their function can be an opportunity to selectively impair cancer cells harboring SF3B1 mutations." (PMID 31634348, 2019). "In contrast, SF3B3 mutations are rare in cancers, and the functional role of SF3B3 in cancer development remains largely unknown." (PMID 38671459, 2024). "Pan-cancer analysis of TCGA data revealed that SF3B3 expression correlated positively with the expression of full-length mTOR-001 isoform." (PMID 38671459, 2024). "P-gp and SF3B3 are among miR-214 target genes and are known to mediate drug resistance and cancer cell proliferation, respectively." (PMID 33613846, 2021). "We demonstrated that the overexpression of the GOLGB1 or SF3B3 promoted aggressive cancer progression such as cell proliferation, invasion, and migration reflecting aggressive behaviors of the recurrent HCC." (PMID 28038442, 2017). "Additional studies in other cancer types may be investigated to test whether targeting SF3B3 could be broadly applied." (PMID 38671459, 2024). "Importantly, we identified SF3B3 as a critical regulator of mTOR splicing and autophagy in multiple cancers." (PMID 38671459, 2024). "Importantly, we identified SF3B3 as a critical regulator of mTOR splicing and autophagy in multiple cancers, including CRC." (PMID 38671459, 2024). "Therefore, mTOR inhibitors might be helpful in the treatment of SF3B3 highly expressed cancers." (PMID 38671459, 2024). "Notably, SF3B3 knockdown markedly increased exon 8 skipping of mTOR and LC3B protein levels in all three cancer cell lines." (PMID 38671459, 2024). "To validate whether JA regulates the cancer spliceosome, we carried out immunoblotting to confirm the expression of SF3B1 and SF3B3 following JA treatment in MCF-7 and MDA-MB-468 cells." (PMID 28198434, 2017). "This study identifies SF3B3 as a negative autophagic regulator across various cancers." (PMID 38671459, 2024). "Interestingly, the analysis revealed that 7 targets (SF3B1, SF3B3, SNRPA, SNRPE, SNRPF, HNRNPA3 and EFTUD2) are physically interacting proteins within the spliceosome complex, suggesting that JA might regulate the cancer spliceosome to induce tumor-specific cell death." (PMID 28198434, 2017).
tumor (9 papers, 2017 to 2024). "Additionally, Qihong Huang identified a novel ribonucleprotein (RNP) complex (hnRNPK, FXR1, FXR2, PUF60, SF3B3), which is required for translational regulation of lncRNA to cause tumor invasion and metastasis." (PMID 34057025, 2021). "Notably, SF3B3 expression demonstrated a positive correlation with MKI67, which encodes a proliferation marker for tumor cells." (PMID 38671459, 2024). "Interestingly, SF3B3 knockdown not only suppressed the primary tumor growth in the cecum, but also inhibited the liver metastasis of LoVo cells." (PMID 38671459, 2024). "Importantly, ectopic expression of SF3B1, SF3B3 or JA treatment induced significant tumor-specific cell death accompanied by the accumulation of unspliced pre-mRNAs." (PMID 28198434, 2017). "This may suggest that SF3B3-regualted autophagy is not limited to tumor cells." (PMID 38671459, 2024). "It is reported that SF3B3 is a key regulator of pre-mRNA splicing of EZH2, therefore regulating tumor development." (PMID 36357564, 2023). "Jerantinine A is a novel indole alkaloid with potent anti-tumor cell proliferative activity by inhibiting microtubulin polymerization, upregulating SF3B1 and SF3B3, and inducing G2/M cell cycle arrest and tumor-specific cell death." (PMID 37007111, 2023). "A higher mTOR exon 8 skipping was observed in tumor tissues compared to matched normal tissues, showing a negative correlation with SF3B3 expression." (PMID 38671459, 2024).
SF3B3 also shares sentences with these, for which no sentence is quoted: cervical cancer (2 papers); esophageal squamous cell carcinoma (2); colorectal cancer (1); lung carcinoma (1); meningioma (1); metastatic disease (1); neurological disorders (1); oral squamous cell carcinoma (1); ovarian carcinoma (1); renal fibrosis (1).